MGARP (mitochondria localized glutamic acid rich protein)
Description:
Plays a role in the trafficking of mitochondria along microtubules. Regulates the kinesin-mediated axonal transport of mitochondria to nerve terminals along microtubules during hypoxia. Participates in the translocation of TRAK2/GRIF1 from the cytoplasm to the mitochondrion. Also plays a role in steroidogenesis through maintenance of mitochondrial abundance and morphology (By similarity). Plays an inhibitory role during neocortex development by regulating mitochondrial morphology, distribution and motility in neocortical neurons (By similarity).
Synonyms: CESP-1; C4orf49; HUMMR; OSAP
Tractability: Antibody: UniProt predicts a signal peptide or a membrane-spanning region.
Gene: Protein-coding gene on chromosome 4 (139,266,165 to 139,280,346, reverse strand). Ensembl gene ENSG00000137463.
Subcellular location: Mitochondrion; Mitochondrion outer membrane; Mitochondrion inner membrane
Subcellular location (Human Protein Atlas): Mitochondria
Gene Ontology:
Molecular function: protein binding
Biological process: anterograde axonal transport; axon development; axonal transport of mitochondrion; cellular response to gonadotropin-releasing hormone; cellular response to hypoxia; cellular response to steroid hormone stimulus; cerebral cortex development; negative regulation of dendrite development; protein localization to mitochondrion; regulation of mitochondrion organization; retrograde axonal transport
Cellular component: mitochondrion; mitochondrial inner membrane; mitochondrial outer membrane; axon cytoplasm
Genetic constraint (gnomAD): Loss-of-function variants: 7 observed, 6.44 expected, observed/expected ratio (o/e) 1.09, 90% interval 0.61 to 1.81. That is too few expected variants to judge how well the gene tolerates losing a copy. Missense variants: 253 observed, 288.44 expected, observed/expected ratio (o/e) 0.88, 90% interval 0.79 to 0.97. Synonymous variants: 103 observed, 114.36 expected, observed/expected ratio (o/e) 0.9, 90% interval 0.77 to 1.06.
Homologues: Orthologues: chimpanzee MGARP (100% identical), macaque MGARP (96% identical), rabbit MGARP (72% identical), pig MGARP (72% identical), dog MGARP (62% identical), rat Mgarp (57% identical), mouse Mgarp (55% identical), tropical clawed frog mgarp (36% identical), zebrafish mgarpa (16% identical).
Diseases named in the same sentence as MGARP in open-access papers:
MGARP is named in the same sentence as 5 diseases in open-access papers, as found by Europe PMC text mining. Sharing a sentence is not in itself a finding about the gene and the disease. The quoted sentences say what the papers report.
autism (1 paper, 2020). Persistent deficits in social interaction and communication and interaction as well as a markedly restricted repertoire of activity and interest as well as repetitive patterns of behavior. "Transcriptome analysis showed new markedly altered genes (e.g., KLHL1, LHX9, and MGARP) and a large number of differential expression genes (DEGs), some of which are related to autism." (PMID 34567661, 2020).
neurodevelopmental disorder (1 paper, 2020). A behavioral and cognitive disorder with onset during the developmental period that involves impaired or aberrant development of intellectual, motor, or social functions. "Thus, the upregulation of MGARP in VPA-exposed cortical organoids could explain mitochondrial impairment observed in neurodevelopmental disorders." (PMID 34567661, 2020).
MGARP also shares sentences with these, for which no sentence is quoted: cancer (1 paper); Infertility (1); lymph node metastasis (1).